INS (insulin)
Diseases named in the same sentence as INS in open-access papers (continued):
Sharing a sentence is not in itself a finding about the gene and the disease.
Insulin resistance (continued). "The homeostasis model assessment of insulin resistance (HOMA-IR) was used for insulin resistance estimation and calculated as fasting insulin (μU/ml) × fasting glucose (mmol/L)/22.5." (PMID 34394128, 2021). "It has been shown in some studies to improve insulin resistance as assessed by the homeostatic model of insulin resistance (HOMA-IR), a static/surrogate measure of insulin sensitivity." (PMID 33854039, 2021). "Homeostatic model assessment for insulin resistance (HOMA-IR) is calculated from the values of fasting glucose and fasting insulin or C-peptide." (PMID 34658643, 2021). "Insulin resistance is one of the pathophysiological hallmarks of NAFLD and, accordingly, plasma insulin levels were almost doubled in subjects with suspected NAFLD in the current study." (PMID 34120339, 2021). "Sitagliptin can increase the pre-insulin function of GLP-1 and improve insulin resistance, thus reducing fatty acid hydrolysis, so, Sitagliptin improves the levels of incretin hormones, thereby affecting fat metabolism." (PMID 34094026, 2021). "Markers of insulin resistance (high BCAA, glutamate, and C3/C5 and low urea cycle AA) at baseline predicted increases in metrics of insulin sensitivity (decreased TG/HDL and increased adiponectin) during lifestyle intervention." (PMID 34277974, 2021). "Increased insulin resistance, AHR, peribranchial and perivascular fibrosis, and macrophages in the BAL; insulin stimulates TGF-β1 expression in bronchial epithelial cells in vivo and in vitro; Anti-TGF-β1 antibody attenuated HFD-induced lung fibrosis." (PMID 35082682, 2021). "Insulin also stimulates the production and secretion of lipoprotein ligase that plays a major role in VLDL clearance, so during insulin resistance, lipoprotein ligase activity is impaired." (PMID 33806509, 2021). "The levels of glucose, insulin, and HOMA-IR index, measured to evaluate insulin resistance, significantly increased in the diabetic group compared with baseline level and control group (P<0.05)." (PMID 34804425, 2021). "With insulin resistance being central in type 2 diabetes pathogenesis, a new alternative in the inhibition of DPP (IV) has proposed in order to stimulate the release of insulin." (PMID 33249946, 2021). "Furthermore, although insulin resistance increases with age and, in older adults without dementia cortical insulin concentration is decreased, in our population the association between insulin resistance brain hypometabolism and grey matter volume was independent of age and gender." (PMID 33597002, 2021). "HI was evaluated by serum fasting insulin (FIN), and IR was evaluated by homeostatic model assessment of insulin resistance index (HOMA-IR)." (PMID 35071255, 2021). "When the ITT test was conducted at the end of week 8, insulin sensitivity was already enhanced in the CDAHFD‐0.1 group, while insulin resistance was induced in the CDAHFD‐0.6 group." (PMID 34390210, 2021). "The results revealed decreases in insulin resistance, serum glucose, TG, TC, serum total antioxidant capacity (TAOC), and fructosamine, while insulin levels and β-cell function improved." (PMID 33435282, 2021). "As insulin in the brain contributes to the control of nutrient homeostasis, cognition, memory, as well as neuromodulatory and neuroprotective effects, alterations of these functional activities may contribute to the manifestation of clinical entities, including central insulin resistance and T2DM." (PMID 34943038, 2021). "A high-fat diet will induce insulin resistance in peripheral tissues related to lipotoxicity, while low-dose STZ (25-30 mg/kg) will induce a mild defect in insulin secretion." (PMID 34475697, 2021). "Women with GDM are prone to dysfunctional insulin-mediated suppression of lipolysis, resulting in exaggerated FFA and glucose production, and severe insulin resistance." (PMID 33923959, 2021).
Insulin resistance (continued). "Based on insulin release during OGTT and HOMA-IR, the supplement appeared to reduce the insulin resistance developed by HFD feeding." (PMID 34359921, 2021). "Insulin resistance is a ubiquitous finding in PCOS and SNPs in genes involved in the insulin signaling pathway are possible candidates that can explain the development of clinical manifestations of PCOS." (PMID 34912452, 2021). "Additionally, a recent randomized control trial proved that RS exercise could improve CV risk factors of obese adolescent girls, including body fat percent, waist circumference (WC), blood pressure, blood glucose, insulin levels, and homeostatic model assessment of insulin resistance (HOMA-IR)." (PMID 34579097, 2021). "HOMA-IR measures insulin-resistance in Wistar rats while HOMA-β measures β-cell function both on the basis of fasting glucose and insulin levels." (PMID 34208508, 2021). "The authors conclude that, while the causal factors of insulin resistance, such as metabolic stress or inflammation due to a high-fat diet, may be directly involved in the acceleration of Aβ accumulation in the brain, insulin signaling does not appear to play a role." (PMID 34576151, 2021). "The insulin levels were significantly increased and an ITT estimating the peripheral insulin resistance was significantly higher in IMM rats than in the CON group." (PMID 33356018, 2021). "However, despite the relationship between phospholipid levels and insulin sensitivity, it has not been established whether these changes are a cause or a consequence of insulin resistance." (PMID 34938272, 2021). "The selective inhibition of the kinase potentiates insulin signaling both in vitro and in vivo suggesting that GRK2 mediates adrenergic insulin resistance while its inhibition increases insulin sensitivity." (PMID 33467677, 2021). "By directly targeting the intracellular insulin signal transduction system, TNF-α can enhance insulin resistance through upregulating suppressor of cytokine signaling 3 (SOCS-3) and inhibiting adiponectin activity." (PMID 33505505, 2021). "Although insulin is a potent activator of overall muscle and whole body BCAA oxidation, much of the work on BCAA metabolism has focussed on insulin resistance/T2DM." (PMID 34354601, 2021). "As regarding to insulin sensitivity and insulin resistance, the proposed mechanism by which IGFBP2 improves insulin sensitivity, is through IGFs/IGFBP2-dependent and independent model." (PMID 33498859, 2021). "The homeostatic model assessment for insulin resistance (HOMA2-IR) and insulin sensitivity (HOMA2-S) significantly differed among the three groups, with the highest values in the T2D group." (PMID 33801208, 2021). "In maternal and cord blood, we measured the insulin concentrations, the Homeostasis Model Assessment (HOMA) for insulin resistance (IR) index, and β-cell activity." (PMID 33602219, 2021). "First, SOCS3 is an important negative regulator of the insulin signalling pathway and SOCS3 upregulation has been involved in insulin resistance." (PMID 34001206, 2021). "Previous studies have demonstrated that FGF21 and adiponectin are involved in the regulation of insulin sensitivity, and disturbance of the FGF21-adiponectin pathway abrogates FGF21-induced improvement of insulin resistance." (PMID 34321008, 2021). "Studies have verified that restriction of calorie consumption leads to reduced levels of insulin and IGF-1, complemented by declined insulin resistance and repressed mTOR pathway." (PMID 33920079, 2021). "The homeostatic model assessment for insulin resistance (HOMA-IR) was determined using fasting glucose and insulin." (PMID 34361925, 2021). "Given that the important hallmarks of obesity are metabolic disorders and insulin resistance, we measured serum TG, TC, LDL, HDL, NEFA, glucose and insulin levels in offspring." (PMID 33955677, 2021).
Insulin resistance (continued). "Insulin resistance in GDM is mediated by various factors, Compared with those in healthy pregnant women, glucose uptake is reduced by approximately half, and insulin sensitivity is decreased approximately 60% in patients with GDM." (PMID 35059395, 2021). "Hepatic insulin resistance is defined by decreased capacity to synthesize glycogen and impaired suppression of glycogenolysis, gluconeogenesis, and DNL in the liver after insulin stimulation." (PMID 34359991, 2021). "Double diabetes possesses symptoms of both type 1 and type 2 diabetes including obesity, insulin resistance, type of latent autoimmune diabetes in youth (LADY) autoantibodies (namely GAD56, IA2), and insulin antibodies." (PMID 33467194, 2021). "Insulin not only increases glucose uptake by peripheral tissues such as muscle and fat, but insulin also decreases endogenous glucose production through suppression of gluconeogenesis in the liver and both processes may be affected differentially by insulin resistance." (PMID 34106350, 2021). "Fasting plasma glucose, serum insulin, triglyceride, ALT, AST, uric acid, white blood cell count, and indices of insulin resistance (TyG, METS-IR, and HOMA-IR) also increased, while adiponectin, HDL-c, and eGFR decreased accordingly." (PMID 35173677, 2021). "FBS-to-FI ratio (FBS/FI), homeostasis model assessment of insulin resistance (HOMA-IR), and the quantitative insulin sensitivity check index (QUICKI) are important indicators of insulin sensitivity for patients with hyperinsulinemia." (PMID 34458674, 2021). "Furthermore, high levels of cortisol are associated with insulin resistance and/or hyperinsulinemia, including increased gluconeogenesis; visceral fat cell growth, carbohydrate intolerance; increased total cholesterol, LDL, and triglycerides; decreased HDL, and impaired insulin secretion." (PMID 33828593, 2021). "In particular, the diet treatment significantly improved BMI, waist circumference, systolic and diastolic blood pressure, fasting glycaemia, fasting insulin and HOMA-IR (homeostasis model assessment of insulin resistance)." (PMID 33686615, 2021). "From a clinical point of view, the contribution of a serum level of insulin and HOMA-IR is the same, as we demonstrated that insulin resistance is a key factor in the development of NASH and thus can be used as a therapeutic target." (PMID 34204225, 2021). "TNF-α induced insulin resistance in an enterocyte cell line of IEC-18 cells, and BME promoted glucose utilization of the insulin-resistant cells." (PMID 33746602, 2021). "We also observed that patients in the DAPA group had a lower homoeostasis model assessment insulin resistance (HOMA-IR) and a higher homoeostasis model assessment B (HOMA-B) value at 1 week and 5 weeks compared to those with insulin therapy, respectively." (PMID 34497852, 2021). "Other models focused on insulin resistance and aimed to explain the PI3K/MTOR network dynamics following insulin stimulation in healthy and diabetic cells." (PMID 34529665, 2021). "There were also positive correlations between LCN2 and parameters of insulin resistance: fasting plasma glucose (FGP), HOMA-IR, fasting plasma insulin (FPI), high-sensitivity C-reactive protein (hs-CRP), total cholesterol, and triglyceride." (PMID 34212049, 2021). "The homeostasis model assessment for insulin resistance (HOMA-IR) ≥ 3.16 and fasting insulin ≥ 15 mU/L was used to determine the outcome variable of IR." (PMID 34666809, 2021). "Studies have shown that C-peptide, serum insulin concentration (SIC), and the homeostasis model assessment of insulin resistance (HOMA-IR) were significantly upregulated in patients with a larger aneurysm diameter, and HbA1c was a high-risk factor for AD." (PMID 35187097, 2021).
Insulin resistance (continued). "It is well known that adipocyte hypertrophy and increased adiponectin secretion in the adipose tissue are responsible for insulin resistance, consistent with the increased circulating FABP4 and insulin levels in Crtc1–/– mice observed in our study." (PMID 33912553, 2021). "This said, the higher fasting insulin combined with unchanged FPG is the reason for the increasing insulin resistance by HOMA seen in the LNS group, which is consistent with more hepatic insulin resistance." (PMID 34657634, 2021). "In this study, we found that PU improved HFD-induced insulin resistance, as supported by the decreased fasting serum insulin levels, HOMA-IR index, and the results of the GTT and ITT, indicating that insulin sensitivity had been improved." (PMID 34262422, 2021). "The VAT/SAT ratio, HOMA-IR (homeostatic model assessment of insulin resistance), HOMA-B (homeostatic model assessment of β-cell function), and CIR30 (corrected insulin response) were calculated." (PMID 34200102, 2021). "With decreased FBG, OGTT-AUC level as well as serum insulin level and HOMA-IR, rats in OBC groups showed improved glycometabolism and insulin resistance." (PMID 35004803, 2021). "Glucose tolerance (GTT) and insulin tolerance testing (ITT) suggested that H-Exo recipient mice become glucose intolerant and showed the impression of insulin resistance." (PMID 33431899, 2021). "The studies show that high (plasma) insulin values in HIV-negative individuals, even with normal glucose tolerance, can indicate insulin resistance and presage the development of T2DM." (PMID 33918016, 2021). "The persistent hyperglycaemia, despite higher circulating insulin levels elicited by BPA, is an indicator of insulin resistance and disrupted glucose homeostasis." (PMID 33467592, 2021). "In the insulin resistance model of L02 hepatocytes induced by various factors (such as palmitic acid, dexamethasone, TNF-α, IL-1β and insulin), the expression of ANGPTL8 increased only in the presence of hyperinsulinaemia." (PMID 34582711, 2021). "This protein is involved in the glucose-stimulated insulin secretion (GSIS) by the control of reactive oxygen species (ROS) production, and its lower expression in T2DM patients promotes insulin resistance." (PMID 34440850, 2021). "As a classical pathway in insulin signal transduction, any defects in the PI3K p110 and AKT activation along with the downstream molecules will lead to insulin resistance." (PMID 34917687, 2021). "Insulin resistance in obesity and T2DM is manifested by decreased insulin-stimulated glucose transport and metabolism in adipocytes and skeletal muscle and by impaired suppression of hepatic glucose output." (PMID 34003397, 2021). "Of interest, they found that subcutaneous WAT grafts ameliorate HFD-induced insulin resistance and markedly reduce the release of several proinflammatory cytokines, while BAT grafts fail to improve insulin sensitivity." (PMID 35052704, 2021). "In Beclin1F121A mice with constitutively active autophagy (described in the previous section), normal insulin signaling to AKT in muscle was preserved during HFD, granting protection from diet-induced insulin resistance." (PMID 34336862, 2021). "In addition, quercetin affected the hypothalamic insulin signaling pathway by upregulating the phosphorylation of insulin receptors (InsRs) and protein kinase (PK) B, also known as Akt, thereby effectively improving insulin resistance in high fructose-induced rats." (PMID 34257817, 2021). "A total of 210 S-T were mainly enriched in the insulin resistance pathway, nonalcoholic fatty liver disease pathway, HIF-1 signaling pathway, PI3K-Akt signaling pathway, insulin signaling pathway, AMPK signaling pathway, etc." (PMID 33936248, 2021).
Insulin resistance (continued). "In obesity, the expansion of adipose tissue can lead to a chronic inflammatory state contributing to the elevated levels of circulating insulin, IGF, and obesity-related insulin resistance, thus creating a more favorable TME for carcinogenesis." (PMID 34350120, 2021). "Glucose tolerance tests (GTT) and insulin tolerance test (ITT) indicated that the clearance of blood glucose and the insulin resistance were both significantly improved by GA-02 treatment (p < 0.001)." (PMID 34526895, 2021). "In T1DM, uncontrolled hyperglycemia and low concentrations of endogenous insulin are the key defects that are involved in the pathogenesis of ED, whereas in T2DM, dyslipidemia and insulin resistance play prominent roles." (PMID 33995040, 2021). "We further assessed effect on glycated hemoglobin (HbA1c), fasting insulin, homeostatic model assessment index for beta-cell function (HOMA-B) and insulin resistance (HOMA-IR)." (PMID 34657634, 2021). "Insulin resistance promoted by a HFD was improved with RR supplementation, albeit only partial restoration of insulin signaling in IngWAT was seen." (PMID 34501954, 2021). "Elevated OGTT-AUC reflects the decrease of glucose tolerance in diabetic rats, the increase of HOMA-IR shows the formation of insulin resistance, with the raised FBG and insulin level, disorder of glucose metabolism in diabetic rats revealed." (PMID 35004803, 2021). "Zinc levels were negatively correlated with leptin, insulin, TNF-α and homeostatic model assessment of insulin resistance (HOMA-IR) values in obese individuals." (PMID 34208404, 2021). "Consistent with this, male sham HFD mice had higher fasting homeostatic model assessment for insulin resistance compared with female sham HFD mice, and this was improved in male GX HFD mice, suggesting increased insulin sensitivity in GX males." (PMID 34599964, 2021). "High concentrations of BCAAs activate the mTORC1/S6K1 kinase pathway, resulting in insulin resistance through the phosphorylation of insulin receptor substrate 1 (IRS-1), leading to blocked insulin signaling." (PMID 34684308, 2021). "High levels of plasma insulin might potentiate cortisol, adrenaline and noradrenaline secretion during hypoglycemia and, in the present study, higher doses of insulin were required to induce hypoglycemia in patients with type 2 diabetes due to pronounced insulin resistance." (PMID 34085953, 2021). "After metabolic labs were processed, obese subjects were stratified by insulin resistance based on calculated HOMA-IR levels (Insulin Sensitive [IS]: HOMA-IR <2; Insulin Resistant [IR]: HOMA-IR >2)." (PMID 33481860, 2021). "Whether the relationship between insulin resistance and small HDLs is causal remains to be seen, but it could be postulated that some of the proteins that are selectively transported by small HDL particles inactivate insulin signalling pathways in skeletal muscle and adipose tissue." (PMID 33918571, 2021). "Physical activity can improve the health outcomes of BC survivors by affecting insulin, IGF, insulin resistance, glucose metabolism, sex hormones, adipokines, inflammatory factors, oxidative stress, and DNA damage repair ability." (PMID 34350120, 2021). "Insulin resistance was induced in rats with a fructose-rich diet and confirmed from baseline analysis of FBS (>250 mg/dl), insulin (>25 μIU/ml), and HOMA-IR (>10)." (PMID 33953863, 2021). "Insulin-mediated IRS tyrosine phosphorylation is the key intermediate in insulin signal transduction and serves as the major target for insulin resistance inducers." (PMID 34445300, 2021). "For ferritin and triglycerides, the slope is moderate and smooth, while, for insulin and HOMA-IR, the slope is steep at a certain value, probably because a point is reached where insulin resistance becomes irreversible, overt T2DM." (PMID 34204225, 2021).